CDC6 (cell division cycle 6)
Diseases named in the same sentence as CDC6 in open-access papers (continued):
Sharing a sentence is not in itself a finding about the gene and the disease.
melanoma (6 papers, 2008 to 2024). A malignant, usually aggressive tumor composed of atypical, neoplastic melanocytes. "We show that loss of interaction with CDC6 occurs when some of the point mutations identified in melanoma samples are introduced into the TTC4 gene." (PMID 18320024, 2008). "Some TTC4 point mutations reported in late stage melanomas lose interaction with CDC6 but still show substantial interaction with Hsp90 and Hsp70." (PMID 18320024, 2008). "In conclusion, CDC6 accelerates the proliferation, migration, and invasion of melanoma cells in vitro." (PMID 39052109, 2024). "The siRNAs targeting CDC6 were transfected into human melanoma cells (A-375 and SK-MEL-28), and western blot assay was conducted to verify the transfection efficiency." (PMID 39052109, 2024). "We observed elevated expression of CDC6 at both transcriptome and protein levels in melanoma samples, which correlated with poorer outcomes in SKCM patients." (PMID 39052109, 2024). "In wound scratch assay, the migrative capacity of the melanoma cells was suppressed by CDC6 knockdown." (PMID 39052109, 2024). "The identified genes, especially CDC6, which plays a crucial role in enhancing melanoma cell proliferation, migration, and invasion, provide valuable insights into potential methylation-based biomarkers." (PMID 39052109, 2024). "The CCK-8 assay showed that CDC6 knockdown inhibited the proliferative ability of the melanoma cells." (PMID 39052109, 2024). "In this study, we aimed to create a novel non-melanoma skin cancer model in zebrafish by co-overexpression of Cdc6 and c-Myc to study their oncogenic mechanisms through the observation on an early onset and visible transformation on the outmost skin layer." (PMID 25051368, 2014). "Furthermore, through in vitro experiments, we demonstrated that CDC6 enhances the proliferation, migration, and invasion abilities of melanoma cells." (PMID 39052109, 2024). "Besides, the Transwell assay revealed that the invasive ability of the melanoma cells with CDC6 knockdown was significantly suppressed." (PMID 39052109, 2024). "The biological role of CDC6 in melanoma cells was investigated by in vitro experiments." (PMID 39052109, 2024). "After conducting an extensive literature review, we observed that cell division cycle 6 (CDC6) has been relatively underexplored in melanoma research compared to other prognostic genes, despite its implication in the initiation and progression of various human tumors." (PMID 39052109, 2024). "Additionally, we validated the prometastatic role of CDC6 in melanoma and identified its methylation sites, showing the critical role of CDC6 in augmenting the proliferative, migratory, and invasive ability of SKCM." (PMID 39052109, 2024). "In this work, we established a novel non-melanoma skin cancer model in zebrafish to study the oncogenic mechanisms of Cdc6 and c-Myc by co-overexpression of both in the outmost skin layer, rendering the practicability in a good cancer model and anti-cancer drug screening." (PMID 25051368, 2014). "As a first step in order to understand if the selected E2F target genes could function as predictor markers of CDK4/6 inhibition resistance, we compared the expression profiles of E2F1, CDC6, DHFR, H2AFZ, MCM2, and ATAD2 among the four canine melanoma cell lines." (PMID 34485433, 2021).
clear cell renal cell carcinoma (5 papers, 2020 to 2024). "As for clear cell renal cell carcinoma (ccRCC), CDC6 was also related to the TMB, immune checkpoint molecules, tumor microenvironment, and immune infiltration." (PMID 39684684, 2024). "CDC6 expression was significantly upregulated in renal clear cell carcinoma tissues compared with adjacent normal renal tissues." (PMID 39684684, 2024). "Here, we evaluate the relationship between CDC6 expression and oncology outcomes in patients with clear cell renal cell carcinoma (ccRCC)." (PMID 34136398, 2021). "High expression of CDC6 predicted poor survival rate of patients with renal clear cell carcinoma and renal papillary cell carcinoma, suggesting that CDC6 may serve as a potential target for RCC management." (PMID 32792963, 2020).
COVID-19 (5 papers, 2021 to 2024). A disease caused by infection with severe acute respiratory syndrome coronavirus 2. "In our study, the levels of CDC6, CDC25C, and KIF15 were down-regulated in both the COVID-19 and SLE datasets, suggesting a better prognosis with these genes." (PMID 37426642, 2023). "Using published data, we use a set of optimized-performance COVID-19 genomic biomarkers (MND1, CDC6, ZNF282) to study the benefits and adverse effects of the BNT162b2 vaccine." (PMID 36366282, 2022). "Genes involved in cell cycle, were over-expressed among COVID-19 compared to both HLTY controls and INFL, with a “hill” pattern (e.g. PTTG1, CDC6, MAD2L1, E2F1)." (PMID 34135895, 2021). "The area under the curve (AUC) values for 6 shared hub genes (CDC6, PLCG1, KIF15, LCK, CDC25C, and RASGRP1) in the SLE dataset to discriminate between patients and healthy controls were greater than 0.61, while those for the COVID-19 dataset were greater than 0.91." (PMID 37426642, 2023).
lung adenocarcinoma (5 papers, 2016 to 2025). A carcinoma that arises from the lung and is characterized by the presence of malignant glandular epithelial cells. "The mRNA expression of CDC6 was considerably elevated in many tumor tissues, such as lung adenocarcinoma (LUAD), compared with normal tissues." (PMID 41339304, 2025). "Importantly, four of the top ten pathways (pathways with ranks 1, 2, 6 and 10) are associated with genes identified as either therapeutic targets for lung adenocarcinoma (Ran and ATR) or as biomarkers of patient prognonsis (CDC6)." (PMID 30541428, 2018).
neuroblastoma (5 papers, 2017 to 2024). Neuroblastoma (NB) is the most common solid, extracranial childhood tumor. "Altogether, these results support the clinical significance of the interaction network formed by CDKN3, CDC6 and CDK4 in neuroblastoma." (PMID 38356706, 2024). "The mRNA content was determined using several multiplex droplet digital PCR (ddPCR) assays for a neuroblastoma-specific gene panel (PHOX2B, TH, CHRNA3) and a cell cycle regulation panel (E2F1, CDC6, ATAD2, H2AFZ, MCM2, DHFR)." (PMID 37046768, 2023).
psoriasis (5 papers, 2019 to 2025). An autoimmune condition characterized by red, well-delineated plaques with silvery scales that are usually on the extensor surfaces and scalp. "Finally, we confirmed that miR-26a-5p triggered cascade downregulation of biomarkers from the IL-23/IL-17A axis associated with psoriasis development while suppressing CDC6 and CCNE1 expression." (PMID 38446584, 2024). "In an in vitro study, CDC6 expression was found to be elevated in psoriatic epidermal cells and inducible by IL-22/STAT3 signaling, a pathway strongly associated with psoriasis pathogenesis." (PMID 39576422, 2025). "BBR effectively inhibited IMQ-induced psoriasis-like skin lesions and reduced CDC6 and phosphorylated STAT3 levels in mice." (PMID 39576422, 2025). "Mechanistic investigations revealed that miR-26a-5p induced a cascade of downregulated genes associated with the IL-23/IL-17A axis, which is known to be critical in psoriasis pathogenesis, while concomitantly suppressing CDC6 and CCNE1 expression." (PMID 38446584, 2024). "Meanwhile, the LORICRIN expression was downregulated while the CDC6 expression was upregulated in skin lesions from patients with psoriasis, demonstrating reduced differentiation and increased proliferation in psoriatic lesions." (PMID 38834617, 2024). "To explore the possible role of CDC6 in keratinocyte in psoriasis, we first examined expression of CDC6 in the affected skin of patients with psoriasis using the public GEO data set (GDS4602)." (PMID 30894513, 2019). "In the present study, we examined the expression of CDC6 in lesional skin of psoriasis and investigated its roles in keratinocytes." (PMID 30894513, 2019). "More importantly, we showed that both mRNA and protein levels of CDC6 were upregulated in epidermal keratinocytes from lesional skin of psoriasis." (PMID 30894513, 2019). "Western blot was further employed to determine CDC6 protein levels, and the result showed that CDC6 protein levels were also increased in lesional skin of psoriasis." (PMID 30894513, 2019). "CDC6, a critical regulator of the prereplication complex assembly in eukaryotic cells, plays a pivotal role in keratinocyte proliferation, although its involvement in psoriasis was previously unclear." (PMID 39576422, 2025). "We also revealed that BBR could inhibit imiquimod-induced STAT3 action, CDC6 upregulation and psoriasis-like skin lesions in mice." (PMID 30894513, 2019). "To further evaluate whether CDC6 expression was upregulated in epidermis of psoriatic lesions, we performed immunohistochemistry on skin biopsies from patients with psoriasis and healthy individuals." (PMID 30894513, 2019). "In summary, we demonstrated that CDC6 is upregulated in epidermis in lesional skin of psoriasis." (PMID 30894513, 2019). "CDC6 is an essential regulator of pre-RC assembly and DNA replication in eukaryotic cells, but its role in proliferation of keratinocytes and psoriasis is unknown." (PMID 30894513, 2019). "Finally, we demonstrated that BBR could inhibit imiquimod-induced psoriasis-like skin lesions and upregulation of CDC6 and p-STAT3 in mice." (PMID 30894513, 2019). "Therefore, CDC6 may be responsible for the aberrant proliferation of keratinocytes in psoriasis and could be targeted for the treatment of psoriasis." (PMID 30894513, 2019). "However, the role of CDC6 in keratinocytes and psoriasis is unknown." (PMID 30894513, 2019). "The analysis showed that expression of CDC6 mRNA is similar in healthy normal and nonlesional skins of psoriasis patients, while it was significantly increased in lesional regions of psoriasis patients." (PMID 30894513, 2019). "CDC6 expression is upregulated in epidermal cells in psoriatic lesions and it could be induced by IL-22/STAT3 signaling, a key signaling pathway involved in the pathogenesis of psoriasis, in keratinocytes." (PMID 30894513, 2019).
squamous cell carcinoma (5 papers, 2008 to 2024). A carcinoma arising from squamous epithelial cells. "Additionally, we also found FBP1 and CDC6 levels were dramatically reduced in skin lesions from patients with squamous cell carcinoma (SCC) using dataset GSE191334, implicating FBP1 might also participate in SCC development." (PMID 38834617, 2024). "The mRNA levels of CDC6, CDT1, MCM2 and CDC45 in 31 cases of precancerous epithelial dysplasia and 33 cases of squamous cell carcinoma of the tongue from formalin-fixed, paraffin-embedded specimens were measured using QRT-PCR." (PMID 19116018, 2008).
cervical carcinoma (4 papers, 2015 to 2023). A carcinoma arising from either the exocervical squamous epithelium or the endocervical glandular epithelium.
liver cancer (4 papers, 2018 to 2025). An epithelial or non-epithelial malignant neoplasm that arises from the liver. "The therapeutic effect of CDC6 KO mediated by PAR‐Lipos against liver cancer was further evaluated according to the same protocol." (PMID 32714743, 2020). "This demonstrated dysregulated expression and a pro-invasion role for CDC6 in liver cancer." (PMID 33173413, 2020). "Statistical analysis of clinical data indicated that the expression levels of hCDC6 (human CDC6) in breast cancer (BRCA) and liver cancer (LIHC) were significantly higher than those in corresponding normal tissues." (PMID 32714743, 2020). "Based on the results of single-cell pseudotime analysis, we examined the changes in the expression levels of the shared pathogenic genes (IGSF3, CENPW, CDC6, CDT1) from adjacent non-tumor cells to liver cancer cells during the continuous process." (PMID 40433415, 2025).
brain cancer (3 papers, 2017 to 2024). A primary or metastatic malignant neoplasm affecting the brain. "For grade 4 glioblastoma brain cancer, CCNB1 was indicated as a part of hub genes (with CDC6, KIF23, and KIF20A) and its expression correlated with prognosis, suggesting it as a potential biomarker for diagnosis and as a target for treatment." (PMID 39409884, 2024). "High levels of CDC6 have been recently reported in around 50% of NSCLC, brain cancer and a subset of mantle cell lymphomas, which suggests that CDC6 has oncogenic properties." (PMID 27861149, 2017).
cervical dysplasia (3 papers, 2006 to 2014). "CDC6 mRNA expression increases in a linear fashion in cervical squamous carcinogenesis, from normal cervix through cervical intraepithelial neoplasia to invasive cervical carcinoma." (PMID 17177999, 2006). "Similar difference in the protein levels of CDC6 and MCM2 was observed in cervical dysplasia." (PMID 19116018, 2008).
viral infection (3 papers, 2010 to 2023). "Therefore, we examined the accumulation of geminin and two other APC substrates, cdc6 and cyclin B1, in mutant virus infection." (PMID 20333247, 2010). "We did not observe significant difference in Cdc6 or a drastic reduction in thymidine kinase protein levels in the UL21a mutant relative to wild-type viral infection (data not shown)." (PMID 22792066, 2012).
B cell lymphoma (2 papers, 2023). "However, it is found that the G1321A polymorphism of CDC6 was associated with decreased risk for B-cell-non-Hodgkin lymphoma, which suggested the role of CDC6 in B cells." (PMID 36599883, 2023). "Interestingly, Cdc6 G1321A polymorphism (V441I, rs13706) was found to affect the risk of B cell lymphoma, and the AG or combined AA/AG genotype was associated with decreased risk for DLBCL, possibly through modulating mRNA secondary structure." (PMID 37833632, 2023). "Our data support CDC6 as a potential novel target for B cell lymphoma treatment, which needs to be further explored." (PMID 37833632, 2023).
brain tumors (2 papers, 2015 to 2024). "In addition, CDC6 overexpression has been shown to promote aggressiveness in cervical, bladder, and brain tumors." (PMID 39184446, 2024). "High levels of CDC6 protein were reported in 55% of brain tumors." (PMID 26317630, 2015).
Cirrhosis (2 papers, 2018 to 2024). A chronic disorder of the liver in which liver tissue becomes scarred and is partially replaced by regenerative nodules and fibrotic tissue resulting in loss of liver function. "Other significantly downregulated genes by proglumide have been implicated as biomarkers in the progression to cirrhosis, such as A1BG (that codes for Alpha-1-B Glycoprotein; 43), Ppbp (that codes for proplatelet basic protein; 44), and CDC6 (Cell Division Cycle 6; 45)." (PMID 38252699, 2024).
colon cancer (2 papers, 2024). "Analysis of dataset GSE29623, an mRNA and microRNA profile in colon cancer, supported that miR-622 positively correlated with signature genes in cell cycle pathway, such as CDC6 (r = 0.421), CDK2 (r = 0.336), CCNE1 (r = 0.423), CCNA2 (r = 0.412), CCNA5 (r = 0.350), and MCM10 (r = 0.423)." (PMID 38166756, 2024).
Ear-patella-short stature syndrome (2 papers, 2023). "Many diseases (Meier-Gorlin Syndrome 5, Meier-Gorlin Syndrome 1) and various types of cancers were found to involve the dysregulation of CDC6." (PMID 37594635, 2023).
glioblastoma (2 papers, 2023 to 2024). The most malignant astrocytic tumor (WHO grade IV). "For instance, the expression of CDC6 was up-regulated in glioblastoma multiforme and strongly correlated with a bad prognostic profile." (PMID 37594635, 2023).
lymphoma (2 papers, 2022 to 2023). A malignant (clonal) proliferation of B- lymphocytes or T- lymphocytes which involves the lymph nodes, bone marrow and/or extranodal sites. "A related study on lymphoma indicated that the CDC6 G1321A polymorphism was associated with a reduced risk of non-Hodgkin lymphoma." (PMID 36531013, 2022). "CDC6 promotes lymphoma cell survival and prevents cell apoptosis, possibly through cell cycle regulation, Bcl2 upregulation and downregulation of Bax and INK4 and E-cadherin." (PMID 37833632, 2023). "However, the clinical significance and mechanisms of action of CDC6 in lymphoma are poorly understood." (PMID 37833632, 2023).
microcephaly (2 papers, 2013 to 2023). A congenital or acquired developmental disorder in which the circumference of the head is smaller than normal for the person's age and sex. "CDC6 is associated with Meier–Gorlin syndrome, a syndrome with microcephaly, short stature, and neurodevelopmental delay (OMIM# 2246909); however, an association with epileptic encephalopathy has only recently been suggested illustrating the flexibility of TE over P sequencing." (PMID 38125836, 2023).
prostate tumor (2 papers, 2015 to 2023). "LINC01088 or CDC6 was upregulated in prostate tumor tissues or cells, whereas miR-22 was downregulated, miR-22 directly targets both LINC01088 and CDC6." (PMID 37501932, 2023).
renal cell carcinoma (2 papers, 2020 to 2024). "In the present study, we identified CDC6 expression as a potential indicator of poor prognosis in patients with renal cell carcinoma." (PMID 39684684, 2024). "Furthermore, CDC6 is related to the infiltration of macrophages and can be used as an independent prognostic factor in patients with renal cell carcinoma." (PMID 39684684, 2024).
SCC of the tongue (2 papers, 2008 to 2024). "The nonparametric receiver operating characteristic analysis suggested that MCM2 and CDC45 had a higher accuracy than CDC6 and CDT1 for distinguishing dysplasia from tongue SCC." (PMID 19116018, 2008). "In other words, MCM2 and CDC45 had a higher accuracy than CDC6 and CDT1 for distinguishing precancerous stages from malignant tongue SCC." (PMID 19116018, 2008). "Therefore, overexpression of CDC6 and CDT1 in SCC of the tongue may be due, at least in part, to an E2F-1 to -3 mediated effect." (PMID 19116018, 2008). "The area under the ROC curve (AUC) was 0.679 for CDC6 (p = 0.032), 0.808 for CDT1 (p = 0.000), 0.933 for MCM2 (p = 0.000) and 0.836 for CDC45 (p = 0.000), indicating that MCM2 and CDC45 were superior to CDC6 and CDT1, and could be used as useful tumor markers in diagnosing tongue SCC." (PMID 19116018, 2008).
African trypanosomiasis (1 paper, 2013). "Since T. cruzi and T. brucei use archaeal-like Orc1/Cdc6 as the initiation factor, screening of specific inhibitors that only target TcOrc1/Cdc6 and TbOrc1/Cdc6 ATPase activities but not that of human pre-RC would greatly benefit the treatment of American and African trypanosomiasis." (PMID 23662735, 2013).
aging (1 paper, 2025). A developmental process that is a deterioration and loss of function over time. "In the context of skin aging, TFPI2 downregulation contributes to senescence by impeding cellular proliferation through the PI3K/Akt/CDC6 axis." (PMID 40361374, 2025).
astrocytic tumor (1 paper, 2015). A glial tumor of the brain or spinal cord showing astrocytic differentiation. "On the basis of these results and on the premise that human CDC6 is essential for initiation of DNA replication, we can infer that the overexpression of CDC6 in astrocytic tumors can aid in cell cycle progression and progression from low-grade to high-grade tumors." (PMID 26317630, 2015). "Therefore, the present study aimed to evaluate the expression and methylation profiles of the genes CDKN2A, CDKN2B, CDC6, Bmi-1, CCND1, and RB1 in astrocytic tumors in the northern region of Brazil." (PMID 26317630, 2015).
bladder urothelial carcinoma (1 paper, 2016). "We examined the expression pattern of Cdc6 in bladder urothelial carcinoma and its correlation with clinicopathological factors and prognosis." (PMID 27246979, 2016). "In this study, we demonstrated elevated Cdc6 expression in bladder urothelial cancer tissues compared to normal bladder tissues." (PMID 27246979, 2016).